IL6 (interleukin 6)
Diseases named in the same sentence as IL6 in open-access papers (continued):
Sharing a sentence is not in itself a finding about the gene and the disease.
periodontitis (continued). "We also confirmed that DMWE inhibited the increased concentrations of TNF-α and IL-6 in the serum of periodontitis-induced rats in a dose-dependent manner." (PMID 36677905, 2023). "In parallel, studies on rats found that periodontitis was aggravated by MetS and that interleukin-6 (IL-6) and interleukin-1 (IL-1) mediated osteoclasts activation." (PMID 37038173, 2023). "A recent study found that saliva of both periodontitis patients and healthy controls increases the production of IL-6 and IL-8 and transepithelial electric resistance of oral epithelial cells by an approximately similar extent." (PMID 38068492, 2023). "HGFs do not express enough IL-6R on the cell surface to adequately bind IL-6 but do express gp130, which can bind to the IL-6/sIL-6R complex in the presence of sIL-6R, such as in periodontitis." (PMID 36834667, 2023). "CRP is a marker of acute or systemic inflammation, which is released in response to different cytokines (such as IL-6, IL-1, and TNF-α) associated with periodontitis." (PMID 36651310, 2023). "Periodontitis elevates the levels of inflammatory cytokines like interleukin-6 (IL-6), interleukin-1 (IL-1), and tumor necrosis factor alpha (TNF-α)." (PMID 38132215, 2023). "Our study emphasizes the previous study concerning the significant effect of IL-6 on increasing CRP levels in chronic periodontitis with CAD." (PMID 37239434, 2023). "In summary, the sequential MI treatment MIM-seq displayed cellular anti-inflammatory effects, reducing secreted PGE2 and IL-6 levels and restoring collagen content in an in vitro model of hGF periodontitis." (PMID 37445663, 2023). "Studies have found that periodontitis can lead to abnormal secretion of visceral adipocytes, specifically increased secretion of the adipokines interleukin-6 (IL-6), tumour necrosis factor-α (TNF-α) and leptin and decreased secretion of adiponectin." (PMID 38129878, 2023). "Increased GCF concentrations of IL-6 were found in pregnant women with periodontitis who later develop preeclampsia." (PMID 37342498, 2023). "Compared to healthy controls, patients with periodontitis exhibit elevated serum IL-6 and CRP levels." (PMID 37448125, 2023). "As expected, the mRNA levels of TNF, IL‐6, and IL‐1β dramatically increased in periodontitis mice as compared with control NT mice, while NAC‐S2 treatment significantly suppressed their expression levels in periodontitis mice." (PMID 37647428, 2023). "The continuous observation of IL-6 levels in monkeys with ligature-induced periodontitis revealed that IL-6 occurred as a response to acute initial periodontitis, but remained low in the progression and resolution phases of the disease." (PMID 37342352, 2023). "Studies about the relationship between IL-6 polymorphisms, CRP with chronic periodontitis, and CAD are limited, including studies on polymorphisms of IL-6-572C/G and CRP+1444 C/T." (PMID 37239434, 2023). "This study aims to compare the salivary and gingival crevicular fluid (GCF) concentrations of five cytokines: IL-1β, IL-6, IL-17A, IL-33, and Tumor Necrosis Factor-alpha (TNF-α) in patients with OSA and their association with periodontitis." (PMID 36967976, 2023). "Similar results were published for IL-1β and IL-6, especially in patients with aggressive periodontitis." (PMID 36983201, 2023). "Our results showed that the IL-6 levels in the mild and moderate–severe periodontitis groups were 11.245 ± SD 8.646 and 12.982 ± 11.752, respectively." (PMID 37239434, 2023). "PFD inhibits alveolar bone loss and the expression of IL-1β, IL-6, and TNF-a in ligature-induced periodontitis in mice." (PMID 37240020, 2023). "Elevated levels of inflammatory markers such as CRP, IL-6, IL-1, IL-8, and TNF-α in the blood of patients with periodontitis are thought to be associated with atherosclerotic lesion formation." (PMID 36904268, 2023).
periodontitis (continued). "Overall, four studies reported that the GCF IL-6 levels of OP patients were higher than those of normal-weight periodontitis patients in the longest follow-up time (MD = 1.69, CI = 0.21–3.17)." (PMID 37798684, 2023). "gingivalis virulence factors arsenal, promoting an inflammatory microenvironment characterized by cytokine production (TNF-α, IL-1β, IL-6), prostaglandins, and metalloproteinases (MMPs) that foster the tissular destruction characteristic of periodontitis." (PMID 36897441, 2023). "We measured the concentrations of the inflammatory cytokines, TNF-α, and IL-6, in the serum of periodontitis-induced rats." (PMID 36677905, 2023). "Patients with periodontitis have been observed with increased levels of IL-6 in serum, saliva, and gingival crevicular fluid." (PMID 37342352, 2023). "The levels of LL-37, IL-6, and pain and periodontal clinical parameters were significantly correlated to the severity of periodontitis." (PMID 37246231, 2023). "Exosomes carrying down‐expressed miR‐223 from salivary enhances IL‐1β and IL‐6 expression in periodontitis." (PMID 36705422, 2023). "The investigation showed significant differences in three cytokines, IL-6 (P < 0.01), IL-10 (P < 0.01), and IL-8 (P < 0.0001), between non-periodontitis and periodontitis patients." (PMID 39697803, 2023). "It has been reported that resistin acts as a proinflammatory molecule by stimulating the secretion of tumor necrosis factor α (TNF-α), interleukin (IL)-6 and IL-12, thereby inducing its own production via a positive feedback cycle during periodontitis." (PMID 38149100, 2023). "Therefore, patients with periodontitis might be especially susceptible to an excess of IL-6." (PMID 37342352, 2023). "In animal models of periodontitis, curcumin down-regulated the inflammatory cytokines interleukin-1β (IL-1β), interleukin-6 (IL-6) and tumor necrosis factor-α (TNF-α) and suppressed bone resorption by the suppression of RANKL expression." (PMID 37372983, 2023). "Our present scRNA-seq data suggest that AG fibroblasts and neutrophils are the primary cellular sources of Il6 during the early and later stages, respectively, of periodontitis development." (PMID 38015204, 2023). "Interleukin-6, a pro-inflammatory mediator, is known to regulate the host response to both periodontitis bacterial infection and obesity-related disorders." (PMID 37798684, 2023). "Compared with the control group, periodontitis mice exhibited a significant increase in proinflammatory cytokine (IL-6, IL-1β, TNF-a, IFN-β) production (p < 0.05)." (PMID 37405166, 2023). "After the data analysis, serum cytokine concentration was extracted from 11 periodontitis studies and the highest reported concentration for IL-1 β level was 114 pg/mL, whilst IL-6’s was 125.4 pg/mL, and TNF-α’s was 202.71 pg/mL." (PMID 37106750, 2023). "In the fifth study, significantly elevated levels of salivary cytokines, including interleukin (IL)-1β, IL-6, and tumor necrosis factor-alpha (TNF-α), were observed in periodontitis patients and strongly associated with clinical parameters." (PMID 38192959, 2023). "This has demonstrated that subjects with gingivitis and periodontitis present a significant increase in the levels of IL-6 and other cytokines involved in the inflammatory response, such as IL-1β and TNF-α, compared to periodontally healthy subjects." (PMID 36770741, 2023). "HuR targets 3′-UTR region of IL-6 mRNA and enhances its stabilization, which promotes the development of inflammation in periodontitis." (PMID 35597446, 2022). "IL-6 and IL-8 levels in gingival crevicular fluid are significantly higher in subjects diagnosed with chronic periodontitis than in healthy controls." (PMID 36289904, 2022). "Our study showed that mice with ligature-induced periodontitis exhibited a significant upregulation of IL-1, IL6, and TNF-α expression, which were downregulated by the administration of fenofibrate, compared with control experimental periodontal disease mice." (PMID 35293424, 2022).
periodontitis (continued). "The expression levels of IL-1β and IL-6 were higher than the other two genes in the periodontitis group and periodontitis with T2DM group." (PMID 36248844, 2022). "High-sensitivity C-reactive protein (hs-CRP) and interleukin 6 (IL-6) were dramatically increased compared with periodontitis patients with NBP and with hypertension (P < 0.05)." (PMID 35813436, 2022). "Many studies have shown that periodontitis usually results in higher systemic levels of C-reactive protein, interleukin (IL)-6, and neutrophils." (PMID 35011503, 2022). "Saliva from periodontitis patients caused a prominent increase in TNF-α and IL-6 levels in RAW 264.7 macrophages, and these increases were significantly mitigated by G3@SeHANs and PAMAM-G3." (PMID 36207325, 2022). "Patients with severe periodontitis exhibit elevated blood levels of endotoxins (e.g., LPS) and pro-inflammatory markers such as IL-1, IL-6 and CRP." (PMID 35200242, 2022). "For example, in patients with periodontitis, Prevotella represented an enhanced ability to induce inflammatory mediators (IL-6, IL-8, and TNF-α)." (PMID 35938126, 2022). "IL-6 is an inflammatory mediator induced by pathogens and other pro-inflammatory cytokines, and has been reported to be elevated in periodontitis." (PMID 35268009, 2022). "Periodontitis-induced free radicals and proinflammatory cytokines (IL6, IL17, TNF, CRP) can even activate the hepatocytes and increase CRP production, increasing the systemic inflammatory burden and AGE formation." (PMID 35625570, 2022). "For example, RBP HuR targets the 3′- untranslated regions (UTR) region of IL-6 mRNA to enhances its stabilization in periodontitis." (PMID 35597446, 2022). "This periodontitis-related bacterium induces oral epithelial cells to express inflammatory mediators (interleukin-6 (IL-6), IL-8, tumor necrosis factor-α (TNF-α), prostaglandin E2, and cyclooxygenase-2) without requiring direct contact with these cells." (PMID 35695679, 2022). "Secondly, although TNFα are the main pro-inflammatory cytokines in experimental periodontitis model, other cytokines such as IL-6 and INF-γ must be studied with PPARα activation in the future." (PMID 35830121, 2022). "TNF-α, IL-1β, and IL-6 levels in the gingival crevicular fluid of patients with periodontitis are significantly higher than those in healthy individuals, and these cytokines decreased significantly after treatment." (PMID 36546940, 2022). "Systemic inflammation, indicated by elevated levels of TNFα, IL-1β, IL-6, and IFNγ in the serum, is clinically present in patients with periodontitis." (PMID 35874771, 2022). "TNF-α and IL-6 are the commonly found bone resorption-related factors and inflammatory cytokines during periodontitis." (PMID 36053353, 2022). "A recent meta-analysis concluded that the GCF levels of IL-6 are significantly increased in patients with chronic periodontitis." (PMID 35268009, 2022). "Salivary levels of miR-1246 in patients with chronic periodontitis were positively correlated with the levels of IL-1β, IL-6, IL-17, TNF-α, MMP-1, MMP-8, TIMP-1, PLI, GI, PD, and AL (P < 0.05)." (PMID 35942384, 2022). "The IL-6 content in saliva is reportedly higher in patients with periodontitis than in healthy patients and is positively correlated with periodontal lesion severity." (PMID 36358132, 2022). "A number of retrospective studies demonstrated a correlation between polymorphisms of interleukins IL-1a, IL-1b, IL-1RN, IL-6, IL-10 as well as TNF-a and the incidence of periodontitis and peri-implant disease." (PMID 35819566, 2022). "Previous studies have drawn different conclusions on the influence of periodontal therapy on serum IL-6 levels in periodontitis patients with CVD." (PMID 36243997, 2022). "The expression of TNF-α and IL-6 in the gingival tissues of experimental rats treated with curcumin was significantly lower than the experimental periodontitis animal." (PMID 35903322, 2022).
periodontitis (continued). "The aim of this in vitro and in vivo study was to investigate the interaction of periodontitis and orthodontic tooth movement on interleukin (IL)-6 and C-X-C motif chemokine 2 (CXCL2)." (PMID 34024010, 2022). "It had been found that there were high levels of IL-1β, IL-6 and IL-17 in the serum of patients with periodontitis or T2D." (PMID 36131931, 2022). "IL-6 and IL-8 are essential pro-inflammatory cytokines involved in the pathogenesis of periodontitis." (PMID 36289904, 2022). "A recent study revealed that periodontitis enhanced gingival levels of IL-6 and CXCL2 in an animal model." (PMID 35478496, 2022). "Our study showed that increases in TNF-α, IL-1, and IL6 were reduced by fenofibrate administration in the ligature-induced experimental periodontitis model." (PMID 35293424, 2022). "LPS is a potent stimulator of inflammation, can produce proinflammatory cytokines such as TNFα, IL-6, and IL-1β, resulting in disturbance of periodontal ligament cell differentiation, and further leads to deep periodontal tissue destruction and periodontitis." (PMID 35546327, 2022). "In a ligature-induced periodontitis rat model, mRNA levels of inflammatory cytokines such as IL-6, IL-1β, TNF-α, RANKL, and OPG were increased within the first week of inducing the disease." (PMID 35628390, 2022). "In fact, human periodontal ligament cells (HPDL cells) collected from patients with chronic periodontitis had higher levels of inflammatory cytokines, including IL-6, TNF-α, and HMGB-1, than HDPL cells collected from healthy individuals." (PMID 36163018, 2022). "The aim of this in vitro and in vivo study was to investigate the single and combined effects of periodontitis and orthodontic tooth movement on IL-6 and CXCL2." (PMID 34024010, 2022). "Immunohistochemistry confirmed the down-regulation of TNF-α and IL-6 expressions by NOD-IN-1 in P. intermedia–induced periodontitis." (PMID 36569059, 2022). "It has been reported that TNF-α, IL-1β, IL-6, and IL-17 are highly expressed in periodontal tissues such as periodontal membranes of patients with chronic periodontitis as the expression level increases with the increase of inflammation." (PMID 35942384, 2022). "This corroborates different investigations showing that periodontitis is associated with systemic inflammation biomarkers such as CRP, IL-1 and IL-6." (PMID 35906340, 2022). "Significant increases in serum levels of TNF-α, and IL-6 were reported in maternal animals with ligature-induced periodontitis, as well as in offspring exposed to maternal periodontitis in the pregnancy and lactation period." (PMID 35269617, 2022). "Further studies are warranted to explain the importance of HGF-macrophage crosstalk in the pathophysiology of periodontitis mediated by IL-6." (PMID 36359741, 2022). "Local application of GPA also suppressed IL-6 production in serum and gingival tissue and bone resorption in a P. gingivalis-induced mouse periodontitis model." (PMID 36551860, 2022). "After three applications of HBD3, ligated sites showed reduced osteoclast and alveolar bone loss, and markers of periodontitis: MMP-9, TNF-α and IL-6." (PMID 35979535, 2022). "In our study, the IL-6 level was significantly higher in grade C periodontitis group than the healthy group (p < 0.005)." (PMID 35368315, 2022). "The effects of cytokines, such as IL-6 and IL-10 in the pathogenesis of bone resorption in periodontitis, are influenced by their levels and interactions." (PMID 35757444, 2022). "For the M1 phenotype, levels of TNF-α and IL-6 increased following exposure to periodontitis saliva, but this increase was significantly reduced by treatment with G3@SeHANs and PAMAM-G3." (PMID 36207325, 2022). "Low-grade bacteremia-induced inflammatory markers, including C-reactive protein and IL-6, were elevated in the serum of patients with periodontitis, resulting in the development of DM and atherosclerosis." (PMID 36359741, 2022).
periodontitis (continued). "IL-6 acts as a proinflammatory cytokine during periodontitis and stimulates osteoclastic differentiation and bone resorption in chronic inflammatory periodontitis." (PMID 36053353, 2022). "The pro-inflammatory cytokines TNF-α, IL-1β, and IL-6 play key roles in the occurrence and development of periodontitis." (PMID 36546940, 2022). "All these results emphasize the importance of IL-6 and its transmembrane (mIL-6R) and soluble (sIL-6R) receptors in the acute phase of periodontitis and in tissue destruction by elevating the activity of enzymes." (PMID 35628348, 2022). "In the present study, we investigated the individual and combined effects of periodontitis and orthodontic tooth movement on IL-6 and CXCL2." (PMID 34024010, 2022). "Evidence suggests that T helper 17 (Th17) cells are drivers of periodontitis pathogenesis and that they are recruited to periodontal lesions by IL-6 and interleukin 23 (IL-23)." (PMID 35628390, 2022). "IL-1α, IL-1β and IL-6 are proinflammatory cytokines that are thought to play a role in periodontitis development." (PMID 35571048, 2022). "The highest IL-6 gene expression level was detected when orthodontic tooth movement was performed in the presence of periodontitis." (PMID 34024010, 2022). "Periodontitis is an inflammatory condition where immune cells produce cytokines, such as IL-1 and IL-6." (PMID 35790921, 2022). "The role of IL-6 during chronic inflammation is still not well understood; however, it is known that in patients with inflammation, such as periodontitis, circulating levels of IL-6 are often increased." (PMID 35270396, 2022). "IL-1 and IL-6 are pro-inflammatory cytokines that play central roles in the early phase of periodontitis." (PMID 36359741, 2022). "Salivary concentrations of IL-6 were shown to be higher in chronic periodontitis patients than in healthy controls." (PMID 35804048, 2022). "Peripheral neutrophils from periodontitis patients release excess IL-1β, IL-8, IL-6, and tumor necrosis factor (TNF-α) when stimulated by periodontal pathogens." (PMID 36294367, 2022). "Concerning oral dysbiosis, resveratrol can reduce P. gingivalis LPS-induced TNF-α, IL-6 and IL-1β production in human periodontal ligament cells aggravating destructive tissue processes in periodontitis and promoting systemic inflammation." (PMID 35327570, 2022). "In periodontitis, aberrant genes highlighted include interleukin-1, interleukin-6, interleukin-10, transforming growth factor-beta (TGF-β), tumor necrosis factor-α (TNF-α), interferon-gamma (IFN-γ), and matrix metalloproteinases (MMPs) among others." (PMID 33869630, 2021). "Macrophage infiltration, levels of inflammatory cytokines such as IL-6, IL-1β, and TNFα, and M1 macrophage polarization were enhanced in anti-Act1 periodontitis mice compared to wildtype periodontitis mice." (PMID 33748112, 2021). "In contrast to microbiome-independent mechanisms observed in health, TH17 expansion in experimental periodontitis was dependent on microbial dysbiosis, as well as IL-6 and IL-23." (PMID 34950607, 2021). "Macrophage polarization toward a higher M1/M2 ratio was shown to be involved in the progression of gingivitis to periodontitis, with sustained IL-1β, IL-6, and TNF-α and diminished IL-10 expression." (PMID 34063147, 2021). "The most established cytokines in periodontitis patients in this regard are IL-1α, IL-β, IL-6, IL-8, and TNF-α." (PMID 34207600, 2021). "Periodontitis increase levels of IL-6 both locally and systemically meaning treatment and prevention of periodontal disease can lower levels of IL-6 and, therefore, improve respiratory outcomes of COVID-19 infection, reducing mortality." (PMID 34562980, 2021). "In one of our included studies, the multivariate analysis showed an association between IL-6 and TNF-α in patients with AD and periodontitis." (PMID 34108875, 2021).